INS (insulin)
Diseases named in the same sentence as INS in open-access papers (continued):
Sharing a sentence is not in itself a finding about the gene and the disease.
Hyperglycemia (continued). "In diabetic patients, the 24 h profile of plasma glucose is impaired and characterized by hyperglycemia in the morning (dawn phenomenon) which is particularly caused by an elevated hepatic glucose production and corresponding increased early morning insulin requirements." (PMID 28272464, 2017). "This hyperglycemia might be due to an IR or pancreatic dysfunction associated with insulin secretion perturbation." (PMID 28255159, 2017). "This change was accompanied by significantly decreased plasma insulin levels (1.51 ± 0.15 ng/ml versus 0.83 ± 0.16 ng/ml for Cre−versus Cre+, p < 0.05), suggesting that the observed hyperglycemia, caused by Pax6 deletion, is likely to be due to insufficient insulin output from pancreatic β cells." (PMID 28377501, 2017). "Interestingly, higher levels of adenosine were found in urine and plasma of insulin deficient diabetic rats, supposing a role for hyperglycemia and insulin in adenosine handling by cells." (PMID 28842605, 2017). "Thus, it is tempting to suggest that the hyperinsulinemia and hyperglycemia associated with insulin-resistant conditions, and clinically associated with T2DM, trigger the observed upregulation of GRK2 levels and activities under such conditions." (PMID 28814745, 2017). "In addition, in our cohort, exogenous insulin administration was associated with a greater increase in c-peptide in response to hyperglycemia." (PMID 28497374, 2017). "Maternal hyperglycemia may cause glucose transition via the placenta, and glucose transition might cause excess fetal insulin secretion." (PMID 29191195, 2017). "Thus, liver insulin resistance which is the reduced sensitivity of the liver to insulin, causes gluconeogenesis and hyperglycemia." (PMID 27095446, 2016). "Diabetes is a metabolic disease characterized by hyperglycaemia resulting from defects in insulin secretion or function, and is associated with the long-term damage, dysfunction, and failure of various organs, especially the eyes, kidneys, nerves, heart, and blood vessels." (PMID 27378920, 2016). "Selective inactivation of Bmal1 in the pancreas or in the β cells causes hyperglycemia due to impaired insulin secretion, and isolated pancreatic islets from adult mice display circadian oscillation in glucose-stimulated insulin secretion which is abrogated by Bmal1 ablation." (PMID 27752300, 2016). "Erenmemisoglu and colleagues found that in mice tricyclic antidepressants might cause hyperglycemia, while selective serotonin reuptake inhibitors might reduce plasma glucose independently of insulin levels." (PMID 27788267, 2016). "Furthermore, insulin should be used when hyperglycemia derives from rejection or other causes of graft failure." (PMID 28702248, 2016). "Both mouse models suggest loss of insulin-mediated intra-islet suppression of glucagon production, and with this in mind, we have made a preliminary exploration of leptin treatment in Akita mice, intended to suppress the hyperglycemia with hyperglucagonemia." (PMID 28702245, 2016). "Insulin use was associated with a higher rate of receiving HP eradication therapy, indicating the requirement of insulin for the control of hyperglycemia which could be deteriorated by HP infection (a real risk factor of gastric cancer)." (PMID 27587088, 2016). "Hyperglycemia as a result of reduced insulin production caused by increased glucagon synthesis (postagression metabolism) might be one explanation for the increased glucose levels." (PMID 27978832, 2016). "Determining the molecular mechanisms underlying the amelioration of hyperglycemia, hyperlipidemia and impaired insulin signaling may aid the development of new drugs for diabetic neuropathy." (PMID 27483315, 2016). "A combination of two drugs may cover the several causes of hyperglycemia, like insulin secretion defect, glucagon over secretion, and insulin resistance." (PMID 27997588, 2016).
Hyperglycemia (continued). "Progression to uremia is associated with decreased insulin sensitivity of peripheral tissues, increased hepatic gluconeogenesis, decreased glucose uptake by skeletal muscle cells, and deficiency of intracellular glycogen synthesis and subsequent hyperglycemia." (PMID 27471550, 2016). "Loss of insulin-mediated intra-islet suppression of glucagon production may be a contributor to hyperglycemia in Akita mice, and leptin treatment appears beneficial in such a circumstance." (PMID 28702245, 2016). "Hyperglycemia-induced oxidative stress causes pancreatic β-cell dysfunction due to pro-inflammatory cytokines which induce the release of insulin counter-regulatory hormones (glucagon, cortisol and growth hormone) leading to increased hepatic gluconeogenesis and hyperglycemia." (PMID 27073901, 2016). "In comparison with crocin alone, insulin treatment alone provided better control of metabolic changes (hyperglycemia and body weight loss) induced by STZ, but partially improved STZ-induced biochemical and histopathological changes when compared with crocin (20 mg/kg)." (PMID 28078246, 2016). "Besides hyperglycaemia, inadequate or abnormal patterns of insulin release can also be caused by pancreatic β-cell impairment." (PMID 28042834, 2016). "In particular, a two-week ISCT was generated on 40,000 virtual unique adult and pediatric patients, showing that, in both adult and pediatric populations, the risk of hypo and hyperglycemia using CGM for insulin dosing was equivalent or even lower than that of using SMBG." (PMID 27941663, 2016). "Third, our observation of significant enrichment was generalizable to non-skeletal phenotypes, as exemplified by significant enrichment for association signals in murine candidate genes for abnormal insulin levels and hyperglycemia in the corresponding human traits." (PMID 27612175, 2016). "Probably, these facts could link the deficient insulin signaling and hyperglycemia in renal cells with increasing levels of the nucleoside and the pathogenesis of DN." (PMID 26808537, 2016). "Hyperglucagonemia, which is believed to derive mainly from a loss of insulin-mediated intra-islet suppression of glucagon production, is increasingly recognized as an important cause of hyperglycemia, and we have reported hyperglucagonemia as a phenotypic feature in MIDY patients." (PMID 28702245, 2016). "Furthermore, another study has reported that fasting hyperglycemia caused a significant decrease in the serum insulin levels due to the damage caused by STZ of β cells in the islets of Langerhans." (PMID 27602318, 2016). "Many studies have shown that a loss of PNS insulin signaling may contribute to DN, similarly, several reports have demonstrated that low-dose insulin (insufficient to reduce hyperglycemia) can have beneficial effects on the signs and symptoms of DN." (PMID 28066166, 2016). "The improved insulin sensitivity after weight loss as evidenced by the lower glucose infusion rates we had to apply to induce hyperglycemia may have contributed to the improved vascular effect of GIP." (PMID 27136446, 2016). "Hyperglycemia can result in altered inflammatory pathways, resistance to insulin, and altered free fatty acid metabolism thus causing endothelial dysfunction, increased platelet production, monocyte activation, foam cell transformation and altered smooth muscle cell migration." (PMID 27111304, 2016). "Thus, attenuated neutrophil function in insulin-insufficient hyperglycemia was associated with reduced B. burgdorferi clearance in target organs." (PMID 27340827, 2016). "Methanolic extract of Ecklonia cava prevented the loss of β-cell mass leading to increased production of insulin whereas octaphlorethol A, a phenolic compound isolated from Ishige foliacea protected pancreatic β-cells damage caused by hyperglycaemia due to streptozotocin treatment." (PMID 26308010, 2015).
Hyperglycemia (continued). "Type 1 diabetes (T1D) is an autoimmune disease in which insulin-producing β cells in the pancreatic islets are destroyed by cytotoxic T lymphocytes, resulting in deficiency of insulin and chronic hyperglycemia requiring lifelong dependence on insulin supplementation." (PMID 26062902, 2015). "Additionally, beta cell-specific KO of Glis3 in adult mice results in the development of hyperglycemia due to an almost total loss of insulin production." (PMID 26147758, 2015). "Hyperglycemia as a risk factor can be defined in many ways; also there are many factors that affect the number of measurements to be taken during each individual study, e.g. hematocrit level, use of insulin therapy." (PMID 25766465, 2015). "We indicate that NADH overproduction due to chronic hyperglycemia would overload complex I, causing elevated levels of ROS production that has been previously postulated to contribute to the impairment of β cell function and insulin secretion." (PMID 26568959, 2015). "The objectives of this study were to determine the acute effects of exogenous GIP (4 pmol/kg/minute) on glycaemia, gastric emptying, glucose absorption, and insulin secretion during enteral nutrition in patients with acute critical illness-associated hyperglycaemia." (PMID 25613747, 2015). "The type 2 diabetes (T2D) is a metabolic disorder characterized by hyperglycemia which may predispose the liver to relative insulin resistance due to inadequate secretion or receptor insensitivity to the endogenous insulin." (PMID 26226632, 2015). "It is caused by defects in insulin secretion or insulin action or both, leading to hyperglycemia." (PMID 26448950, 2015). "The protective effects of high fibre diet on attenuation of inflammation may be partly explained by the reduction of oxidative stress caused by hyperglycemia, dyslipidemia as well as improvement of insulin sensitivity." (PMID 26308010, 2015). "Interestingly, the effects of hyperglycemia on β-cell dedifferentiation, loss of insulin content and glucagon expression can be reversed by tight control of blood glucose." (PMID 25982967, 2015). "Surprisingly, bmf deficiency was found to exacerbate hyperglycemia in both diabetic male and hyperglycemic female mice, and ultimately resulted in a decreased glucose-stimulated insulin response, implicating a role for Bmf in glucose homeostasis regulation independent of an effect on beta-cell loss." (PMID 27551471, 2015). "So, both nicotine-induced islet cell loss and decrease in insulin sensitivity may lead to hyperglycaemia and concomitant higher glycated haemoglobin (HbA1C), as observed in our study." (PMID 27486368, 2015). "DGKδ deficiency leads to hyperglycemia, peripheral insulin resistance, and metabolic inflexibility." (PMID 25847921, 2015). "Therefore, in the author’s opinion, delaying the insulin injection for high-fat meals would cause unacceptable postprandial hyperglycaemia." (PMID 26202844, 2015). "Thus, hyperglycemia by stimulating insulin biosynthesis and ROS production causes ER stress in these cells." (PMID 25668518, 2015). "Similarly, a previous animal study showed that vitamin D deficiency or VDR knockout impaired the ability of insulin secretion and induced hyperglycemia." (PMID 25774877, 2015). "Mice deficient in Elvovl6 showed lesser frequencies of hyperglycemia, hyperinsulinemia, and hyperleptinemia and could regulate insulin sensitivity through adjustments in their hepatic fatty acid compositions." (PMID 26592433, 2015). "Hyperglycemia and associated relative deficiency of insulin secretion may negatively modulate a wide array of cardiovascular risk factors, including redox imbalance and increased oxidative stress." (PMID 25945353, 2015).
Hyperglycemia (continued). "T2DM is one of the most prevalent chronic diseases related to MS and is characterized by chronic high glucose contained in the blood (hyperglycemia) caused by the inability of the body to produce insulin or the inability of the cells to respond to the insulin produced by the pancreas." (PMID 26587016, 2015). "The underlying mechanisms for glucocorticoid-induced hyperglycemia include increased hepatic endogenous glucose production, reduced insulin-stimulated glucose uptake in skeletal muscle, increased visceral fat deposition and insulin resistance." (PMID 25883713, 2015). "Loss of UCP2 improves insulin secretion and decreases hyperglycemia in leptin-deficient mice." (PMID 26064426, 2015). "It is characterized by hyperglycemia caused by defects in insulin secretion and/or insulin action." (PMID 26666374, 2015). "Although it is commonly accepted that hyperglycemia is the main contributing factor to the pathogenesis of diabetic complications, studies have implicated the brain insulin resistance or defective brain insulin signaling in neurodegenerative diseases." (PMID 24764190, 2014). "The underlying causes of hyperglycemia during critical illness are attributed to the increased hepatic glucose production and impaired glucose consumption by peripheral tissues as well as insufficient pancreatic insulin production." (PMID 24899891, 2014). "Type 1 diabetes (T1D) is a chronic (auto)immune disease that causes a specific destruction of most insulin-producing pancreatic beta cells, leading to overt hyperglycemia, a need for lifelong exogenous insulin replacement therapy and a high risk for developing debilitating chronic complications." (PMID 25005747, 2014). "Mild to moderate hyperglycemia associated with reduced insulin levels was found." (PMID 25385439, 2014). "Also, a short TCF7L2 mRNA variant in subcutaneous fat is associated with hyperglycemia and impaired insulin action in adipose tissue." (PMID 25379510, 2014). "To determine whether the tubular damage was caused by hyperglycemia, we administered insulin (glargine at a dose of 0.5–2 U daily) and STZ for 2 weeks, which normalized their blood glucose levels but did not mitigate the damage seen in RAMP2+/− kidneys." (PMID 24505304, 2014). "This situation may result in increased glycaemic variability as well as an increased risk of hyperglycaemia and hypoglycaemia during the first 36 hours of treatment due to greater hour-to-hour SI variability with increased insulin resistance." (PMID 25349023, 2014). "Thus, the STZ-treated mice exhibited the classic insulin-deficient diabetic signs of hyperglycemia, polydipsia, polyphagia and weight loss." (PMID 24764190, 2014). "Causes of severe or acute hyperglycemia based on the insulin regimens." (PMID 25181406, 2014). "Also, consistent with the HYP mice hypoinsulinemia and hyperglycemia a complete loss of insulin with hyperglycemia in diabetes type 1 patients (DM1) is associated with a loss of bone mineral density." (PMID 24839967, 2014). "Examples of studies which have investigated medicine initiation as a proxy for an adverse medicine event include, insulin initiation as a proxy for acute hyperglycaemia associated with olanzapine initiation, and antitussive medicine initiation as a proxy for cough associated with ACE inhibitors." (PMID 24886247, 2014). "Indeed, disruption of the XBP1 gene in pancreatic β-cells in mice using the RIP-Cre system resulted in hyperglycemia and abnormal β-cell function caused by decreased insulin secretion, decreased insulin granule content and impaired insulin processing." (PMID 25011481, 2014). "The present trial provides evidence that the hyperglycemia of pasireotide is caused by a reduction in serum insulin, and another recent study found that the reduction of insulin is accompanied by a reduction in glucagon-like peptide-1 (GLP-1) and glucose-dependent insulinotropic peptide (GIP)." (PMID 25385439, 2014).
Hyperglycemia (continued). "Controlling stress hyperglycemia in trauma patients has been shown to improve mortality, but can be challenging due to insulin resistance and increased risk of hypoglycemic episodes." (PMID 25472607, 2014). "DM is a metabolic disorder characterized by hyperglycemia which may predispose the liver to relative insulin resistant due to inadequate secretion or receptor insensitivity to endogenous insulin." (PMID 24918094, 2014). "In contrast, the multicentre trial of insulin infusion reported that although insulin infusion reduced mean glucose concentrations and reduced hyperglycaemia, it resulted in an increase in the risk of death before 28 days and an increase in the proportion of neonates with a hypoglycaemic episode." (PMID 24548745, 2014). "Importantly, these insulin+ crypt cells can sense glucose levels and release insulin in response to high glucose, a property that can ameliorate the hyperglycemia caused by STZ-induced β cell ablation in vivo." (PMID 24613355, 2014). "As pasireotide-related hyperglycemia is associated with both decreased insulin secretion and a reduced incretin response, anti-hyperglycemic treatment in patients with Cushing’s disease treated with pasireotide should preferentially address these two pathophysiological mechanisms." (PMID 23564338, 2014). "Similarly, hyperglycemia caused by inadequate insulin action results in the activation of carbohydrate response element binding protein (CREBP), which activates L-type pyruvate kinase and lipogenic genes in hepatocytes." (PMID 24688399, 2014). "As for insulin secretagogues, sulfonylureas improve hyperglycemia, but can cause serious hypoglycemia, have little effect on hyperlipidemia and lipid abnormalities, and may increase cardiovascular risk." (PMID 26237474, 2014). "Along with aging, db/db mice are shown to exhibit the exhaustion of pancreatic β-cells because of long-standing glucose toxicity attributed to severe hyperglycemia and subsequently exhibit progressive decrease in serum insulin levels and loss of body weight gain." (PMID 25344694, 2014). "The identification of factors associated with the insulin regimens used in managing severe or acute hyperglycemia may contribute towards achieving optimal glycemic control in T2DM patients." (PMID 25181406, 2014). "Also, more recent large scale clinical studies have clearly underlined its high effectiveness in reducing postprandial hyperglycemia and glucose variability, both as mono-therapy or in combination with any other blood glucose-lowering drug, including insulin." (PMID 24742256, 2014). "In this case, OS figures as the connection between hyperglycemia and the physiopathology linked to diabetes, and may be the common pathway by which hyperglycemia and IR induce a decrease in insulin activity." (PMID 23385234, 2013). "The alternating states of intra and interprandial hyperglycemia could be caused by a high amount of these circulating (auto)antibodies sequestering the insulin, and thus inhibiting its activity on the target tissues." (PMID 24386337, 2013). "In conclusion, presently available in vivo data in both humans and rodents clearly indicate that GALNT2 is down-regulated in insulin resistant diabetic individuals and suggest, together with in vitro data, that such an association is, at least partly, secondary to hyperglycemia." (PMID 23894607, 2013). "Altered digestion and absorption of dietary carbohydrate, depletion of glycogen storage, increased gluconeogenesis and over output hepatic glucose, β-cell dysfunction, insulin resistance of peripheral tissue and defect in insulin signaling pathways are more important causes of hyperglycemia." (PMID 23938049, 2013). "Therefore, the improvement of glucose-stimulated insulin secretion is associated with the amelioration of hyperglycemia." (PMID 24223662, 2013).